SOCS2 (suppressor of cytokine signaling 2)
Diseases named in the same sentence as SOCS2 in open-access papers (continued):
Sharing a sentence is not in itself a finding about the gene and the disease.
acromegaly (3 papers, 2020 to 2021). Acromegaly is an acquired disorder related to excessive production of growth hormone (GH) and characterized by progressive somatic disfigurement (mainly involving the face and extremities) and systemic manifestations. "For preoperative acromegaly, SOCS2, cullin-5 and Rbx-2 showed high diagnostic accuracies with 0.91, 0.96 and 0.96, respectively." (PMID 33671326, 2021). "The changes of all ECS-complex proteins in postoperative acromegaly patients and of SOCS2 and EloB in postoperative GHD patients are smaller in comparison to the preoperative groups, which indicates a detectable attenuation of disease severity after surgery." (PMID 33671326, 2021). "In our study, the median of SOCS2 in acromegaly patients over 60 years was increased by 15% compared to controls, while it was increased by 57% in patients below 60 years (p = 0.008)." (PMID 33671326, 2021). "A connection between SOCS2 and acromegaly has already been proven, when significant increases in SOCS2 expression were detected in adipose tissue of acromegalic patients." (PMID 33671326, 2021). "Preoperative acromegaly patients were characterized by higher levels of SOCS2 (1128.8 ± 471.0 pg/mL, p = 0.003), cullin-5 (60.99 ± 30.29 ng/mL, p = 0.001) and Rbx-2 (56.4 ± 31.1 pg/mL, p = 0.0002) compared to controls." (PMID 33671326, 2021). "SOCS2 knockout mice (SOCS2−/−) have increased GH sensitivity and display acromegaly features with higher lean body mass and organ sizes than their wild-type littermates." (PMID 32349250, 2020). "The significant elevations of SOCS2, cullin-5 and Rbx-2 in the preoperative acromegaly group show that these proteins might be candidates for disease detection." (PMID 33671326, 2021). "Still, SOCS2 showed a good SEN and SPEC in postoperative acromegaly (0.87 and 1.0), that translated to the highest AUC in that subgroup (0.90)." (PMID 33671326, 2021). "Unfortunately, comparable statistics of IGF-1 for acromegaly have not been found, but our results suggest an excellent diagnostic performance using the three ECS-complex proteins SOCS2, cullin-5 and Rbx-2 in conjunction." (PMID 33671326, 2021). "Accordingly, the predominantly elevated concentrations of SOCS2 in the preoperative acromegaly patients are apparently not sufficient to fulfill its biological protective function against the elevated levels of circulating GH." (PMID 33671326, 2021). "However, the inhibitory action of high SOCS2 levels apparently did not stop the development of acromegaly." (PMID 33671326, 2021).
Autoimmunity (3 papers, 2018 to 2024). The occurrence of an immune reaction against the organism's own cells or tissues. "In addition, tryptophan metabolites also signal through the AHR in astrocytes and reduce CNS autoimmunity via the Suppressor of Cytokine Signaling 2 (SOCS2)-mediated inhibition of NF-κB-driven inflammation." (PMID 37834203, 2023). "SOCS2 has important roles in the immune system, especially in autoimmunity and infection." (PMID 30723477, 2018). "Therefore, targeting the IL-6/IL-21/SOCS2/STAT5 pathways to restore NK-cell function against autoimmunity may hold therapeutic promise for MG." (PMID 39346912, 2024). "Inhibition of IL-6/IL-21/SOCS2/STAT5 pathway and recovery of NK-cell ability to inhibit autoimmunity may be a new direction in the treatment of MG." (PMID 39346912, 2024).
breast tumors (3 papers, 2010 to 2024). "SOCS2 was generally upregulated in primary breast tumors that developed bone metastasis." (PMID 20696077, 2010). "This is achieved by increasing the expression of the suppressor of cytokine signaling 2 (SOCS2), which efficiently suppresses the development and metastasis of breast neoplasms." (PMID 39371092, 2024).
chronic kidney disease (3 papers, 2018 to 2025). Impairment of the renal function secondary to chronic kidney damage persisting for three or more months. "In the 5/6 nephrectomy mouse model of chronic kidney disease, silencing of SOCS2, a negative regulator of GH action, was shown to overcome CKD-related growth retardation without worsening kidney function." (PMID 34943879, 2021). "In rodent models of chronic kidney disease there is increased Socs2 gene expression in liver and muscle, which may contribute to impaired phosphorylation and nuclear translocation of GH-activated STAT proteins and the development of GH resistance." (PMID 29343614, 2018).
diabetes (3 papers, 2019 to 2024). "SOCS2 is an attractive therapeutic target due to its links to cancer, diabetes, neurological and inflammatory diseases." (PMID 31182716, 2019).
esophageal squamous cell carcinoma (3 papers, 2021 to 2023). Esophageal squamous cell carcinoma (ESCC) is a type of esophageal carcinoma (EC) that can affect any part of the esophagus, but is usually located in the upper or middle third. "WDFY3-AS2 participated in the development and progression of oesophageal squamous cell carcinoma (ESCC) by regulating miR-2355-5p/SOCS2 axis, which suggested that WDFY3-AS2 might be an underlying predictor and novel therapeutic target for ESCC patients." (PMID 36217201, 2022).
experimental autoimmune encephalomyelitis (3 papers, 2018 to 2025). An autoimmune demyelinating disease of the central nervous system that is produced experimentally in animals by the injection of homogenized brain or spinal cord in Freund's adjuvant. "Socs2 contributes to the induction of neuroinflammation in the early and peak phases of experimental autoimmune encephalomyelitis." (PMID 39062636, 2024). "In experimental autoimmune encephalomyelitis (EAE) mouse models, SOCS2 has been found to induce neuroinflammation during the initial and peak phases of EAE." (PMID 41021615, 2025). "In experimental autoimmune encephalomyelitis (EAE), type 1 interferon (IFN-I) signaling in astrocytes reduces disease scores and inflammation via AHR and the suppressor of cytokine signaling 2 (SOCS2)." (PMID 30060580, 2018).
liver disease (3 papers, 2019 to 2024). "Further studies are required to explore the potential preventive and therapeutic strategies of SOCS2 for this common liver disease." (PMID 34803490, 2021). "Among these, suppressor of cytokine signaling 2 (SOCS2) and TRIM31 were analyzed separately due to their likely involvement in persistent viral infection and liver disease development." (PMID 39211324, 2024). "Although STAT3 signaling might be more important than STAT5 in HCC progression and miR-196b could activate STAT3 by targeting SOCS2 in macrophages, previous work showed that importance of JAK2/STAT5 signaling in liver metabolism, liver diseases, and HCC36." (PMID 30988277, 2019).
oral cancer (3 papers, 2018 to 2024). "SOCS2, suppressor of the cytokine signaling, has been identified as a novel target of miR-424-5p, which its overexpression in oral cancer cells can promote the cell migration and invasion through SOCS2 repression." (PMID 34319042, 2021). "A recent study reported that in oral cancer miR-424-5p directly targets supressor of cytokine signaling gene (SOCS2) and modulates STAT5 signaling, expression of matrix metalloproteinase, cell migration, and invasion." (PMID 29482431, 2018). "In oral cancer, miR-424 targets STAT5, involved in cellular aberrant invasion and SOCS2, a suppressor of cytokine signaling." (PMID 39272848, 2024).
renal fibrosis (3 papers, 2017 to 2022). A final common manifestation of a wide variety of chronic kidney diseases characterized by glomerulosclerosis and tubulointerstitial fibrosis. "Based on previous studies, we determined that injury caused by crystal deposition is frequently accompanied by renal fibrosis and that THBS1, ITGA11, and SOCS2 can affect the fibrotic process." (PMID 34997271, 2022).
acute leukemia (2 papers, 2014 to 2015). A clonal (malignant) hematopoietic disorder with an acute onset, affecting the bone marrow and the peripheral blood. "The highest and widespread SOCS2 expression in BM hematopoietic populations was associated with aggressive acute leukemia subsets, namely acute myeloid (AML) and lymphoblastic leukemias (ALL) with MLL rearrangments and BCR/ABL abnormalities." (PMID 26909359, 2015). "As this step marks the transition to an acute leukemia, the overlapping genes (CEBPB, FOS, FOSB, IL8, S100A12, SOCS2) might be involved in the aggressiveness of MLL-AF9 myeloid leukemia blasts." (PMID 24517546, 2014). "Such STAT-independent mechanism might explain the expression of SOCS2 in acute leukemia subsets with MLL rearrangements, which are not strictly associated to constitutive STATs activation." (PMID 26909359, 2015).
cholangiocarcinoma (2 papers, 2018 to 2019). A carcinoma that arises from the intrahepatic biliary tree (intrahepatic cholangiocarcinoma) or from the junction, or adjacent to the junction, of the right and left hepatic ducts (hilar cholangiocarcinoma). "We also data mining using public TCGA data sets to examine the expression of NR1H4 and SOCS2 in Liver Hepatocellular Carcinoma (LIHC) and Cholangiocarcinoma." (PMID 30787420, 2019).
Cognitive impairment (2 papers, 2019 to 2025). Abnormal cognition is characterized by deficits in thinking, reasoning, or remembering. "In diabetic rat models, PF ameliorates cognitive impairment by modulating the Suppressor of Cytokine Signaling 2 (SOCS2)/IRS-1 signaling pathway." (PMID 40260393, 2025).
eosinophilia (2 papers, 2013 to 2015). "CD4+ T cells from Schistosoma mansoni-infected SOCS2-/- mice expressed high Type-2 responses after challenge: high levels of IgE, Type-2 responses, eosinophilia and inflammatory pathology compared to wild-type individuals." (PMID 25867089, 2015). "Interestingly, SOCS2-/- mice display marked eosinophilia, raising the possibility that low SOCS2 expression in the CEL patient is lineage restricted." (PMID 23372669, 2013).
glioblastoma (2 papers, 2015 to 2022). The most malignant astrocytic tumor (WHO grade IV). "m6A methylation and its enzyme METTL3 are upregulated in glioblastoma stem cells and HCC, and the high expression of METTL3 induces SOCS2 degradation by m6A methylation, thus promoting tumor cell growth and survival." (PMID 36401285, 2022).
hepatoblastoma (2 papers, 2023). Hepatoblastoma (HB) is a malignant hepatic tumor and is the most common pediatric liver cancer. "Consistently, we found that SOCS2 was associated with hepatoblastoma vascular invasion and tumor metastasis by immunohistochemistry." (PMID 38071211, 2023). "Because SOCS2 is both associated with hepatoblastoma metastasis and has the largest differential expression fold (|logFC|= 1.87), we selected SOCS2 as the molecule for subsequent experimental analysis in this study." (PMID 38071211, 2023). "We found that SOCS2 was a gene down-regulated in hepatoblastoma and associated with HB metastasis through bioinformatics." (PMID 38071211, 2023). "We found that SOCS2 was closely associated with hepatoblastoma metastasis by WGCNA." (PMID 38071211, 2023). "SOCS2 is associated with hepatoblastoma vascular invasion and tumor metastasis." (PMID 38071211, 2023). "In this study, we obtained RNA-seq and clinical data of hepatoblastoma from the GEO database and used WGCNA combined with differential gene expression analysis to find that SOCS2 is associated with hepatoblastoma metastasis." (PMID 38071211, 2023). "Our study describes the possible biological role of SOCS2 in hepatoblastoma metastasis and provides new evidence for the treatment of children with hepatoblastoma." (PMID 38071211, 2023). "The results showed that overexpression of SOCS2 impaired formation of hepatoblastoma lung metastasis in vivo." (PMID 38071211, 2023). "Then we found that SOCS2 expression was significantly reduced in hepatoblastoma both at the mRNA and protein levels by qRT-PCR and Western blot." (PMID 38071211, 2023). "Overexpression of SOCS2 inhibited the migration and invasion of hepatoblastoma cells, while knockdown of SOCS2 expression promoted these malignant phenotypes." (PMID 38071211, 2023). "In conclusion, our study reports for the first time the significance of the SOCS2/JAK2/STAT5 axis in hepatoblastoma metastasis." (PMID 38071211, 2023). "Our study found that SOCS2 inhibits the migration and invasion of hepatoblastoma cells by inhibiting the JAK2/STAT5 signaling pathway." (PMID 38071211, 2023). "Through GSEA, we found that SOCS2 can affect epithelial mesenchymal transformation in hepatoblastoma." (PMID 38071211, 2023). "Through Transwell experiment, we found that si-SOCS2 can promote the migration and invasion of HB cells, while Federatinib can reverse the effect of si-SOCS2 on the migration and invasion of hepatoblastoma." (PMID 38071211, 2023). "To explore the underlying biological function of SOCS2 in hepatoblastoma, we first detected the mRNA expression levels of SOCS2 in HB cells (Huh6, HepG2) and hepatocytes LO2 by qRT-PCR, and the results showed that SOCS2 was significantly lower in HB cells than in LO2 cell line." (PMID 38071211, 2023). "We used qRT-PCR to analyze the mRNA levels of SOCS2 in tumor tissues and paired paraneoplastic liver tissues of 12 children with hepatoblastoma in our hospital, and we found that the mRNA levels of SOCS2 in HB tissues were significantly lower than those in paraneoplastic liver tissues." (PMID 38071211, 2023). "Therefore, the effect of SOCS2 on hepatoblastoma metastasis became the subject of our experiments to be studied." (PMID 38071211, 2023). "We found that SOCS2 inhibits hepatoblastoma invasion and metastasis through cellular experiments." (PMID 38071211, 2023). "Our study found low expression of SOCS2 in hepatoblastoma tissues and cells." (PMID 38071211, 2023). "We explored the expression of SOCS2 in hepatoblastoma for the first time and proposed that SOCS2 may be one of the important regulators of hepatoblastoma metastasis." (PMID 38071211, 2023). "To further explore the downstream mechanisms of SOCS2 in inhibiting HB metastasis, we performed GSEA analysis of hepatoblastoma gene expression profiles in GSE131329 to identify the biological processes and signaling pathways affected by SOCS2." (PMID 38071211, 2023).
hepatoblastoma (continued). "SOCS2 can inhibit EMT in HB cell lines, further demonstrating its ability to suppress the invasion and metastasis of hepatoblastoma." (PMID 38071211, 2023). "However, no studies of SOCS2 have been reported in hepatoblastoma, and the specific regulatory mechanisms are yet less known." (PMID 38071211, 2023).
influenza (2 papers, 2014 to 2019). An acute viral infection of the respiratory tract, occurring in isolated cases, in epidemics, or in pandemics; it is caused by serologically different strains of viruses (influenzaviruses) designated A, B, and C, has a 3-day incubation period, and usually lasts for 3 to 10 days. "SOCS1 and SOCS3 expression has been associated with symptomatic influenza infection, whereas SOCS2 and SOCS5 have been linked to asymptomatic disease." (PMID 24809749, 2014). "SOCS2 mRNA was reduced both in influenza-infected (MA+Inf+) and in non-infected cells (MA+Inf−)." (PMID 31796757, 2019).
intestinal tumors (2 papers, 2021 to 2023). "SOCS2 deficiency facilitates spontaneous progression of intestinal tumors that are driven both by AP-1 activation and mutations in the E. coli/β-catenin pathway." (PMID 37346073, 2023). "Deletion of SOCS2 promotes spontaneous development of intestinal tumors in mice." (PMID 34120621, 2021).
Lipid Metabolism Disorder (2 papers, 2020 to 2024). "Overall, a lack of Thr hinders the initiation of the JAK-STAT pathway, diminishing the propagation of the feedback-controlled signals SOCS1 and SOCS2 mRNA, potentially causing irregular downstream gene expression associated with lipid metabolism and lipid metabolism disorders." (PMID 39125712, 2024).
myeloid leukemia (2 papers, 2014 to 2019). A clonal proliferation of myeloid cells and their precursors in the bone marrow, peripheral blood, and spleen. "SOCS2 expression was also analyzed in a curated NCBI GEO dataset of myeloid leukemia patients." (PMID 31775389, 2019).
non-small cell lung carcinoma (2 papers, 2022 to 2026). A group of at least three distinct histological types of lung cancer, including non-small cell squamous cell carcinoma, adenocarcinoma, and large cell carcinoma. "For example, SOCS2 is targeted by miR-578, miR-875, and miR-H9-5p and suppresses the malignant behavior of non-small cell lung cancer cells." (PMID 35037826, 2022).
oral squamous cell carcinoma (2 papers, 2018 to 2021). "It was reported that miR-424-5p expression was essential in mediating IL-8/STAT5/SOCS2 pathway in inducing cell migration and cellular invasiveness in oral squamous cell carcinoma." (PMID 33985567, 2021).
pancreatic cancer (2 papers, 2015 to 2023). "MiR-532-3p has a low expression in pancreatic cancer, but its overexpression can inhibit the tumor progression via DNMT3A-dependent inhibition of SOCS2 methylation." (PMID 37085288, 2023). "Finally, our data suggests that Cav-1 depletion in pancreatic cancer cells affects various pathways, particularly the JAK/STAT pathway, by decreasing activation of JAK2 and STAT3 and by increasing SOCS2, PIAS3, and DUSP5 inhibitory signals." (PMID 26065715, 2015).
periodontitis (2 papers, 2022 to 2024). An acute or chronic inflammatory process that affects the tissues that surround and support the teeth. "Taken together, SOCS1, SOCS2 and SOCS3 genes have been found to be dysregulated in the circulation of patients with periodontitis." (PMID 36456933, 2022).
uremia (2 papers, 2018). A clinical syndrome associated with the retention of renal waste products or uremic toxins in the blood. "Intervention strategies to reduce uremic cachexia are associated with amelioration of the uremia-associated increase in Socs2 expression." (PMID 29343614, 2018).
active tuberculosis (1 paper, 2017). "Our results showed that active tuberculosis subjects had higher levels of SOCS-3 mRNA, lower expressions of SOCS-2, -4, -5, -6, -7, and cytokine-inducible SH2-containing protein-1 (CIS-1) mRNAs, but not SOCS-1 mRNA than healthy and LTBI subjects." (PMID 28430824, 2017).
anemia (1 paper, 2012). A reduction in the number of red blood cells, the amount of hemoglobin, and/or the volume of packed red blood cells. "Socs2, plus five additional targets, further proved to comprise new EPOR/Jak2/Stat5 response genes (which are important for erythropoiesis during anemia)." (PMID 22808010, 2012).
Arthritis (1 paper, 2024). Inflammation of a joint. "On the contrary, in an acute arthritis model, Socs2-/- macrophages exhibited reduced efferocytosis, but only for large peritoneal macrophages (F4/80high)." (PMID 39185412, 2024).
autism (1 paper, 2019). Persistent deficits in social interaction and communication and interaction as well as a markedly restricted repertoire of activity and interest as well as repetitive patterns of behavior. "It is worth noting that ISLR2 and SOCS2 are critically involved in regulating typical axon guidance and neuronal differentiation during neural development, processes recently shown to be disturbed in the neocortex of children with autism." (PMID 31681403, 2019).
autoimmune disease (1 paper, 2025). A disorder resulting from loss of function or tissue destruction of an organ or multiple organs, arising from humoral or cellular immune responses of the individual to their own tissue constituents. "The pathogenic mechanisms of autoimmune diseases are complex, and SOCS proteins, particularly SOCS1, SOCS2, SOCS3, and SOCS5, regulate cytokine receptor signaling through distinct mechanisms, thereby participating in the development and progression of autoimmune diseases." (PMID 40755762, 2025).